CAV1 (caveolin 1)
Diseases named in the same sentence as CAV1 in open-access papers (continued):
Sharing a sentence is not in itself a finding about the gene and the disease.
Obesity (65 papers, 2009 to 2025). Accumulation of substantial excess body fat. "In cases of obesity, there is a marked increase in Cav-1 expression, which is associated with elevated levels of pro-inflammatory cytokines like TNF-α and the activation of NF-κB." (PMID 40358155, 2025). "We aimed to define the inflammatory mediators that influence CAV1 gene regulation and the associated mechanisms in obesity." (PMID 37048092, 2023). "To evaluate the role of CAV1 in obesity-associated metabolic inflammation, we analyzed the association between CAV1 gene expression and the expression of various inflammatory cytokines in obese participants." (PMID 37048092, 2023). "Over the past decades, the CAV1 protein, owing to its role in regulating various signaling cascades, has shown immense potential as a therapeutic target for obesity and obesity-associated metabolic inflammation." (PMID 37048092, 2023). "Fat consumption can change the effect of Cav-1 polymorphism function on obesity and metabolic syndrome." (PMID 36517810, 2022). "In the present study, we investigated the interaction between HBI and BMI-GRS, including MC4R (rs17782313), CAV-1 (rs38 07992), and Cry1 (rs2287161) on abdominal obesity and markers for metabolically associated obesity status in overweight and obese women." (PMID 36167582, 2022). "Caveolin-1 (CAV1) variants have been suggested to be associated with obesity and related metabolic disorders, but information based on human studies is limited." (PMID 30622557, 2018). "CAV1-deficient mice have been reported to exhibit increased levels of triglycerides and free fatty acids, predisposing them to hyperlipidaemia and obesity." (PMID 30622557, 2018). "In this study, saliva samples were used as specimens to analyze the association of the CAV1 rs1997623 SNP with metabolic complications related to obesity." (PMID 30622557, 2018). "Meanwhile, CAV1 deficiency also leads to obesity accompanied by abnormalities in lipid metabolism, insulin resistance, hypertriglyceridemia, and dysregulated non-shivering thermogenesis." (PMID 24608114, 2014). "It was previously reported that CAV1 expression in human adipose tissue is up-regulated in obesity and obesity-associated type 2 diabetes." (PMID 24608114, 2014). "CAV1-deficient mice are resistant to diet-induced obesity and have defects in adipose tissue lipolysis, while humans with caveolin-1 mutations show a severe lipodystrophy." (PMID 23049990, 2012). "This putative role is completely consistent with the loss of diet-induced obesity in mice with a targeted inactivation of either Cav1 or Ptrf (Cavin)." (PMID 20574519, 2010). "Caveolin-1 of lipid rafts is localized within plasma membrane invaginations that have a critical role in cell signaling, protein trafficking, and uptake of fatty acids; caveolin-1 deficient mice are resistant to diet induced obesity." (PMID 20300478, 2009). "CAV-1 and the leptin receptor are co-localized in keratinocytes, and CAV-1 silenced human keratinocytes produce more IL-6 by co-stimulation with leptin and IL-17, suggesting that obesity deteriorates psoriasis by enhancing cytokine production in CAV-1 deficient psoriasis keratinocytes." (PMID 36532050, 2022). "According to our knowledge, there are no comparable studies that compare HBI and markers such as MC4R (rs17782313), CAV-1 (rs3807992), and Cry-1 (rs2287161) with abdominal obesity and obesity-related metabolic risk factors in overweight and obese women across time." (PMID 36167582, 2022). "The present study also might have a clinical implication, highlighting the potential of applying this finding in the prevention and treatment of CAV1-linked obesity and cardiovascular disease that is the result of high VFL." (PMID 34384444, 2021). "Indeed, the involvement of CAV1 or its genetic variants in obesity and insulin resistance offers a pathophysiological clue for future understanding of its role in tumour glucose and fatty acid metabolism." (PMID 27852311, 2016).
Obesity (continued). "In addition, it suggests that increased secretion of IL-6 characterizes different types of adipose tissue metabolic stress, i.e. diet induced obesity and CAV1 deficiency." (PMID 23049990, 2012). "The finding of decreased CAV-1 gene expression in adipocytes from obese subjects, and the associations with lipogenic genes and triglycerides will help to understand the alterations of intracellular signaling and lipid synthesis in obesity." (PMID 20226013, 2010). "Obesity is associated with increased sDPP-4 levels, which also leads to adipocyte insulin resistance through mechanisms related to the interactions with caveolin-1 (Cav-1), expressed on the cell surface of adipocytes and adipose tissue macrophages, as well as increased hepatic insulin resistance." (PMID 40072115, 2025). "There have been many studies on the relationship between diet patterns and types of obesity, but there are a few studies that have been done on the relationship between dietary intake especially fat intake and body fat distribution pattern, and also CAV-1 polymorphism." (PMID 34753501, 2021). "Finally, as pro-inflammatory cytokine production by adipose tissue is a hallmark of obesity, we analysed the production of IL-6 by adipose tissue explants from CAV1+/+ and CAV1−/− mice that had been maintained on a high-fat diet (HFD) or a control diet for 12 weeks." (PMID 23049990, 2012). "Furthermore, CAV1−/− mice are resistant to diet-induced obesity and show a mild lipodystrophy, and human mutations in CAV1 are associated with a severe lipodystrophic phenotype, suggesting defects in lipid storage, adipogenesis or in adipose tissue homeostasis." (PMID 23049990, 2012). "Investigation involving Cav-1 knockout mice demonstrates a lean phenotype, resistance to obesity from high-fat diets, and notable decreases in adipose tissue mass." (PMID 40358155, 2025). "In MS patients presenting with clinical symptoms such as systemic arterial hypertension, dyslipidemia, obesity, and increased abdominal circumference, there is a marked upregulation of CAV-1 mRNA expression." (PMID 36879344, 2023). "Several studies have provided strong evidence demonstrating the role of CAV1 in the pathophysiology of various diseases, particularly regarding the increase of CAV1 expression in obesity." (PMID 37048092, 2023). "Global Caveolin-1 deletion (Cav1−/−) mice showed protection against diet-induced obesity, partly due to the higher presence of steatorrhea." (PMID 36817150, 2023). "On the other hand, according to recent research, CAV1 expression is increased in human obesity, suggesting that leptin can play a crucial role." (PMID 36151575, 2022). "There are three forms of caveolin: caveolin 1, caveolin 2, and caveolin 3, which are expressed differently and can all affect obesity." (PMID 36517810, 2022). "The obesity-related gene phosphatase and tensin homolog was a direct target of miR-216a, which regulates expression of adiponectin receptor 1, caveolin-1, caveolin-2, and PPARγ." (PMID 35711801, 2022). "For example, high SFA intake can increase the adverse effects of Cav-1 in terms of metabolic syndrome and obesity." (PMID 36517810, 2022). "This cross-sectional study investigated the relationship of genetic risk score by obesity-related genetic markers, including MC4R (rs17782313), CAV-1 (rs3807992), and Cry-1 (rs2287161), with cardiometabolic risk factors in overweight and obese women." (PMID 36324080, 2022). "Caveolin-1 null mice were lean and resistant to diet-induced obesity due to reduced/atrophic fat deposits." (PMID 34917687, 2021). "Similar results (the reduced expression of caveolin-1) have been reported in the omental adipose tissue of individuals who were overweight or had obesity." (PMID 34917687, 2021). "IR is the consequence of obesity which is seen in CAV1 knock-out mice and is consistent with the medical descriptions of overweight and obese subjects by showing decreased insulin sensitivity in adipose tissues." (PMID 34001235, 2021).
Obesity (continued). "CAV1 is targeted by several miRs, which are upregulated in obesity and IR, like miR-103/107 and miR-221/222." (PMID 34199293, 2021). "In summary, we found that the expression of NOX5 in the endothelium under obesity conditions is able to induce an upregulation of important insulin signalling intermediaries, such as Ir-B, Cav1, and Glut4 in the neighbouring adipose cells." (PMID 33800461, 2021). "Cav-1 inhibits eNOS and HFD-induced obesity increases vascular Cav-1 expression and accompanies impaired NO-mediated vasodilatation." (PMID 34456860, 2021). "More recent work showed that in human subjects enrolled in a trial of 8 weeks of diet-induced obesity, adipocyte expansion response correlated with initial CAV1 expression in the collected subcutaneous adipose tissue." (PMID 32082483, 2020). "Both high-fat diets produced similar degrees of obesity and reduced localization of endothelial nitric oxide synthase (eNOS) in caveolin-1- (cav-1-) containing lipid rafts." (PMID 31534971, 2019). "Some of the many abnormalities found in Cav1 KO mice (e.g., pulmonary defects, vascular dysfunction, obesity) have also been found in patients with ciliary dysfunction caused by the mutation of ciliary genes." (PMID 30718762, 2019). "One study indicated that CAV1-knockout (CAV1-KO) mice were resistant to high fat diet (HFD)-induced obesity." (PMID 28570612, 2017). "Caveolin-1 is also induced by micro-RNAs up-regulated in obesity (miR103, miR107), and their overexpression induces insulin-resistance in an entirely caveolin-1 dependent manner." (PMID 29202762, 2017). "In humans, CAV1 mutations result in lipodystrophies and CAV1KO display a phenotype of partial lipodystrophy and resistance to obesity." (PMID 27272971, 2016). "Although previous studies have indicated that Cav1 KO mice are resistant to HFD-induced obesity, there is a controversy concerning the role of CAV1 in lipogenesis." (PMID 24608114, 2014). "In conjunction with the present data, an earlier report demonstrated the anti-obesity effects of CAV1, as evidenced by reduced Cav1 expression in visceral adipose tissue of obese patients." (PMID 24608114, 2014). "Previously, we observed increased expression of CAV1 in adipose tissues of obesity- resistant SD male rats fed a HFD." (PMID 24608114, 2014). "Targeted inactivation of either Cav1 or Ptrf results in phenotypes of diet-induced obesity resistance or lipodystrophy in mice." (PMID 24039822, 2013). "Attenuated PKA-mediated signaling to HSL, loss of PLIN1a and increased secretion of IL-6 were also observed in adipose tissue explants of CAV1+/+ mice with diet-induced obesity." (PMID 23049990, 2012). "For instance, NPC1 heterozygous (NPC1+/-) human fibroblasts have increased expression of caveolin-1, which serves as a protein marker for obesity and T2DM." (PMID 22043166, 2011). "Future studies with a larger sample size are warranted to decipher the exact crosstalk between CAV1 and TNF-α and the mechanism by which CAV1 plays an important role in transmitting signals from the cell surface via intracellular signaling pathways that regulate inflammation in obesity." (PMID 37048092, 2023). "In the context of obesity and metabolic syndromes, CAV1 regulation and association with inflammatory markers are not well defined." (PMID 37048092, 2023). "Moreover, obesity increases the expression of caveolin-1, a major component of the caveolae (small membrane invaginations), which attenuates leptin-dependent adiponectin secretion." (PMID 36520252, 2023). "Moreover, CAV1 plays a crucial role in adipose tissue regulation, which is central to development of metabolic syndrome and obesity." (PMID 37017811, 2023). "IFI16, ERBB2, VIM (vimentin) and CAV1 are crucial factors for advancement of obesity." (PMID 36837510, 2023).
Obesity (continued). "Hence, because of the impact of the CAV-1 gene with oxidative stress, it seems that adherence to hPDI could be capable of lowering the metabolic markers, and, as a result, reducing the likelihood of metabolic diseases in women with obesity carrying a risk the allele of ‘A’." (PMID 35641515, 2022). "CAV1 is a transmembrane scaffolding protein that controls essential cell functions such as proliferation, apoptosis, cell division, and transcytosis via a variety of signaling pathways and the progression of atherosclerosis and obesity." (PMID 36151575, 2022). "Moreover, elevated levels of CAV1 expression are seen in individuals with high abdominal circumference and obesity compared to healthy individuals." (PMID 36497195, 2022). "It has been reported that in the human population, genetic variations in CAV-1 have been related to obesity and metabolic disorder, and also depletion of CAV-1 and reduction in the number of caveolae have been related to diseases including cancer and cardiovascular and pulmonary diseases." (PMID 34753501, 2021). "Similarly, diet-induced obesity increased melanoma progression in male C57BL/6J mice by enhancing Cav-1 and FASN expression in tumors." (PMID 34199293, 2021). "Thus, this suggests that downregulation of caveolin-1 in periepididymal adipose tissue can contribute to the pathogenesis of obesity and insulin resistance." (PMID 34917687, 2021). "Nevertheless, there is controversy concerning the role of CAV1 in lipogenesis and obesity because CAV1 gene expression was found to be significantly decreased in the visceral adipose tissue of obese subjects while the findings of another study were contradictory." (PMID 28570612, 2017). "Although still poorly understood, the mechanistic link between obesity, CAV1 and cancer may be partly due to increased adipokine activity." (PMID 27852311, 2016). "CAV1 expression, therefore, apparently contribute to both insulin sensitivity and obesity." (PMID 27852311, 2016). "Resistance to diet-induced obesity is one of the phenotypes of Cav1-null mice." (PMID 24608114, 2014). "The high expression of Cav-1 in mature adipocytes is something already well established Indeed, previous works from our group had also shown an increase of Cav-1 mRNA and protein expression in whole white adipose tissue, and in isolated adipocytes of rats with a diet-induced model of obesity." (PMID 24751908, 2014). "Despite this recent progress, the precise roles of CAV1 remain unclear, especially in the development of obesity." (PMID 24608114, 2014). "For instance, CAV-1 gene expression has been detected in macrophages under the influence of lipopolysaccharide, a bacterial product known to be increased in human obesity." (PMID 20226013, 2010). "In contrast, the absence of Cav-1 offers protection against obesity caused by diet." (PMID 40358155, 2025). "Thus, CAV1-enriched adipocytes in obese individuals might have a greater capacity for lipid storage, which is a characteristic clinical trait of obesity." (PMID 37048092, 2023). "A previous study reported an increase in CAV1 expression in the AT of obese individuals, with or without T2DM, and an association between CAV1 and several inflammatory markers, suggesting a prospective role for CAV1 in obesity-related chronic low-grade inflammation, called metabolic inflammation." (PMID 37048092, 2023). "The role of CAV1 in obesity may be more prominent in women than in men." (PMID 37017811, 2023). "Therefore, we sought to examine whether PDI intakes may affect the relationship between CAV-1 (rs3807992) and metabolic factors, as well as serum inflammatory markers and anthropometric measures, in women with obesity." (PMID 35641515, 2022). "Thus, whether in obesity and insulin resistance, understanding the activity of CAV1 could shed light on its role in metabolism that may be applicable in cancer." (PMID 27852311, 2016).
Obesity (continued). "Moreover, we also postulate that CAV1 may serve as an important player affecting sex dimorphism in the development of obesity and other metabolic diseases." (PMID 24608114, 2014). "Intestinal specific-Caveolin-1 deletion (Cav1iEC−KO) mice decreased circulating free FAs and low-density lipoproteins cholesterol levels, preventing HFD-induced obesity and rapid increase in low-density lipoproteins cholesterol." (PMID 36817150, 2023). "The interplay between CAV1 and the TNF-α signaling pathway is intriguing and has potential as a target for therapeutic interventions in obesity and metabolic syndromes." (PMID 37048092, 2023). "CAV1-null mice had lower fat mass at older age, were resistant to HFD-induced obesity, had lower hepatic lipid accumulation, and had decreased metabolic flexibility compared to wild-type mice." (PMID 32082483, 2020). "To clarify distinct roles of CAV1 in sex-dependent obesity development, we investigated the effects of high fat diet (HFD) and sex steroid hormones on CAV1 expression in adipose tissues of male and female rats." (PMID 24608114, 2014). "In our study, we found a positive correlation between CAV1 expression and CXCLs (CXCL9, CXCL10, and CXCL11); this could be explained by the proinflammatory role and heightened presence of CXCLs in obesity." (PMID 37048092, 2023). "Moreover, we report that when obesity was controlled by using pharmacological or dietary interventions, the levels of FASN, Cav-1, and P-gp were reduced which correlates with improvement in the effectiveness of DTIC on ectopic tumors in mice." (PMID 27980732, 2016). "However, changes in caveolin-1 are not universal in obesity, some dietary interventions may also augment caveolin-1, and distinct from caveolin-3, cardiac expression of caveolin-1 appears repressed with medium-chain triglyceride but not palmitate supplementation." (PMID 29202762, 2017).